CTLA4 (cytotoxic T-lymphocyte associated protein 4)
Diseases named in the same sentence as CTLA4 in open-access papers (continued):
Sharing a sentence is not in itself a finding about the gene and the disease.
colitis (continued). "CD4+T cells are the main T cell subset in CTLA-4-induced colitis patients, while CD8+T cells are dominant in PD-1-induced colitis." (PMID 36189293, 2022). "The combination of anti-CTLA-4 and PD-L1 in the metareview was noted to have a higher incidence rate (13.6% of patients experienced any grade of colitis, and 9.4% experienced grade 3 or 4 colitis)." (PMID 36612082, 2022). "Another study found higher proportion of CD8 T cells in anti-PD-1-induced colitis versus greater CD4 T cells in anti-CTLA-4-induced colitis." (PMID 35474500, 2022). "It appears that colitis and hypophysitis are more common irAEs when treated with anti-CTLA-4, whereas pneumonitis and thyroiditis occur more frequently with anti-PD-1 therapy." (PMID 35327411, 2022). "The most common fatal IRAE with anti–CTLA-4 therapy was colitis (70%), whereas pneumonitis (35%), hepatitis (22%), and neurotoxicity (15%) were most often seen with anti–PD-1/anti–PD-L1 therapy." (PMID 35015209, 2022). "The combination therapy such as dual PD-1/PD-L1 and CTLA4 blockade can also lead to severe irAEs such as colitis, pneumonitis, hypophysitis, and thyroiditis." (PMID 36159789, 2022). "CD4 TH-17 cells secreting IL-17, IL-6, and IL-8 appear in patients who develop grade >3 colitis (with anti CTLA-4)." (PMID 35774996, 2022). "With CTLA-4, symptoms typically start manifesting within 5 to 8 weeks, whereas with anti-PD-1 or PD-L1 treatment, colitis typically occurs 3 to 6 months after initiating treatment." (PMID 36612082, 2022). "For patients treated with anti-CTLA-4 therapy, colitis of any grade was noted in 9.1% of patients, whereas 6.8% experienced grade 3 or 4 colitis." (PMID 36612082, 2022). "For CTLA-4-targeting ICIs, the most common irAEs are rash, pruritis, liver toxicity, diarrhea, colitis, and hypophysitis; for PD-1/PD-L1-targeting ICIs, the most common irAEs are cutaneous or gastrointestinal in nature." (PMID 35565190, 2022). "Colitis is reported in 7–9% of patients receiving anti-CTLA4, 1–4% of patients receiving anti-PD1/PD-L1, and 26% of patients treated with the combination." (PMID 35328239, 2022). "Similar to combination treatment, colitis was the most frequent event that led to treatment discontinuation in anti-CTLA4 alone (18.4% and 14.7%, respectively)." (PMID 34208218, 2021). "ICI-induced colitis occurs most frequently following combined inhibition of PD-1 and CTLA-4, with some reporting incidence of up to 32%." (PMID 35047501, 2021). "A low baseline proportion of peripheral blood CD4+ Tregs has been reported to be associated with anti-CTLA-4-related colitis, while eosinophils had already been found in biopsy specimens from patients with anti-CTLA-4-induced hepatitis, rash and colitis." (PMID 34790123, 2021). "Patients who had a gut microbiome rich in Firmicutes had longer progression-free survival (PFS) and overall survival (OS) and had increased occurrence of anti-CTLA-4 induced colitis." (PMID 34522484, 2021). "For instance, pneumonitis and thyroiditis appear to be more common with anti-PD-1 therapy, while colitis and hypophysitis seem to be more common with anti-CTLA-4 therapy." (PMID 33670634, 2021). "Colitis of any grade, which most commonly presents with diarrhea, has been reported in 30-40% of patients treated with ipilimumab, while severe colitis/diarrhea is seen in up to 7.6-17% patients on anti-CTLA4 treatment." (PMID 35154081, 2021). "We find that in all patient groups, the majority of colon-derived CD8+ T cells are TRM cells, and that in anti–CTLA-4/PD-1 colitis, the highest activation levels are seen in TRM cells." (PMID 34147519, 2021). "Compared to other immune checkpoint inhibitors, irAE colitis induced by anti-CTLA-4 are frequent, potentially severe and resemble IBD, whereas those induced by PD-1 blockade seem to be less frequent and clinically more diverse." (PMID 34778085, 2021).
colitis (continued). "Microbial community reconstruction was observed in both patients with a notable enrichment of Bifidobacterium, which was previously illustrated its ability to abrogate CTLA-4-blockade-induced colitis in mice." (PMID 33435800, 2021). "It is now evident that the risk of an adverse event differs markedly between drug classes, with colitis occurring less frequently after PD-L1 inhibitors than after CTLA-4 drugs and most often when the two agents are used together." (PMID 33923423, 2021). "Severe colitis has only been reported in 1-2% patients after anti-PD-1/PD-L1 treatment, which is much less frequent than after anti-CTLA4 therapy." (PMID 35154081, 2021). "We also provide a direct comparison with idiopathic UC and include analysis of anti–PD-1 monotherapy colitis and anti–CTLA-4/PD-1 gastritis." (PMID 34147519, 2021). "As the most common type, colitis more commonly occurs after the administration of anti-CTLA-4 antibodies (7–12%) than that of anti-PD-1/PD-L1 antibodies (3%)." (PMID 34912213, 2021). "The incidence of colitis was 0.7%–1.6% for anti-PD-1, 5.7%–9.1% for anti-CTLA-4% and 13.6% for the combination of both therapies." (PMID 34778085, 2021). "Similar to the reports for CIP, the combination of CTLA-4 and anti-PD-1/PD-L1 treatment increased the incidence from 0.89% of grade 3 colitis to 3%–5% for combination therapy." (PMID 34660286, 2021). "A study that compared anti-CTLA-4-induced colitis and ulcerative colitis (UC) showed a higher incidence and greater severity of crypt distortion in the former than in UC." (PMID 33923423, 2021). "We performed an extended flow cytometric panel to further characterize the CD8+ TRM cells in anti–CTLA-4/PD-1 colitis." (PMID 34147519, 2021). "We had previously seen a rapid resolution of refractory anti–CTLA-4/PD-1 colitis with FMT treatment in a different patient, with corresponding decreases in CD8+ TRM cell activation." (PMID 34147519, 2021). "Of note, colitis, rash and hypophysitis were more common with CTLA-4 inhibitors, whereas arthralgia, pneumonitis, vitiligo, and hypothyroidism were more common with PD-1 inhibitors." (PMID 34094910, 2021). "With CTLA-4 therapy, the rate of colitis is reported to be 5.7–9.1%, with an incidence of grade 3 colitis of 4.1–6.8%." (PMID 33923423, 2021). "Our scRNASeq experiments confirm that CD8+ TRM cells are enriched in ICI-colitis, and display the highest proportion of immune checkpoint transcripts, including CTLA4 and PCDC1 (PD-1)." (PMID 34147519, 2021). "Anti-CTLA-4 therapy induced colitis displays acute inflammation that includes: neutrophilic inflammation with intraepithelial lymphocytes, and crypt epithelial cell apoptosis on histology." (PMID 34221257, 2021). "As expected, colitis more frequently occurred in patients receiving anti-PD-1/PD-L1 plus anti-CTLA-4 antibodies (ROR025 1.7, IC025 0.5) than either single agent alone." (PMID 34912213, 2021). "The 2015 Vetizou study found that repletion of B. fragilis and B. cepacia improved CTLA-4 ICI efficacy in germ-free animal models and simultaneously reduced the risk of developing ICI-induced colitis." (PMID 34360663, 2021). "The all-grade incidence of colitis was 5.7%–39.1% for CTLA-4 inhibitors and 0.7%–31.6% for PD-1/PD-L1 inhibitors." (PMID 34992611, 2021). "We have demonstrated by Nanostring and bulk RNASeq that IFNG signaling pathways are enriched in anti–CTLA-4/PD-1 colitis, but the source of IFNG message cannot be determined at a bulk RNASeq level." (PMID 34147519, 2021). "Specific microbial metabolic pathways, such as polyamine transport and vitamin B synthesis, were found to be predictive for resistance to colitis induced by CTLA-4 blockade, as well as a Bacteroidetes-rich phylotype." (PMID 34790123, 2021). "Diarrhea, colitis, mucosal erythema and ulceration, infections, are well described for CTLA-4 inhibitors, less for anti-PD-1 antibodies." (PMID 34790123, 2021).
colitis (continued). "In contrast, only 11% (95% CI 7–15%) had colitis when receiving combination therapy with PD-1/PD-L1 and CTLA-4, of which only 15% (95% CI 8–22%) were of a more severe grade (grade 3–5)." (PMID 33923423, 2021). "Their study showed gut microbiome rich in the Bacteroides genus had an inadequate response to anti-CTLA-4 treatment and remained free of colitis." (PMID 34522484, 2021). "The risks of colitis, hepatobiliary disorders, and pancreatitis were higher with anti-CTLA-4 treatment than that with anti-PD-1 (ROR025 2.6, 1.3, and 1.1, respectively) or anti-PD-L1 treatment (ROR025 4.8, 1.3, and 1.3, respectively)." (PMID 34912213, 2021). "Among all the genetic backgrounds, B6/lpr mice treated with anti-CTLA-4 and anti-PD-1 antibodies developed more substantial hepatitis, pancreatitis, colitis, and pneumonitis characterized by organ infiltration of immune cells." (PMID 33571254, 2021). "In agreement with this, colitis is one of the most common side-effects of immune checkpoint blockade with anti-CTLA-4 in cancer." (PMID 34421921, 2021). "We confirm that the canonical JAK/STAT components of IFNG signaling are up-regulated in anti–CTLA-4/PD-1 colitis compared to controls." (PMID 34147519, 2021). "In anti-CTLA-4 trials, the mortality rates were approximately 1%; one third of these were deaths following GI events, especially colitis, and colonic perforation." (PMID 33923423, 2021). "CD8+ TRM cell activation anti–CTLA-4/PD-1 colitis correlates with clinical, endoscopic, and histopathologic findings, and the response to treatment over time." (PMID 34147519, 2021). "The strong and beneficial response would be presented in patients with the abundance of F. prausnitzii receiving anti-CTLA-4 and/or anti-PD-1 inhibitors, possibly with the cost of immunotherapy-induced colitis." (PMID 34992611, 2021). "For example, colitis and diarrhea as irAE are seen more often with anti-CTLA4 therapy than with anti-PD-1/PD-L1 therapy." (PMID 34360795, 2021). "Melanoma patients with greater bacteria abundance from the Bacteroidetes phylum were less likely to develop colitis under the treatment of anti-CTLA-4 inhibitors." (PMID 32665852, 2020). "Next, we used the DSS colitis model to test the effect of tissue damage on blood gut-homing T cells under CTLA-4-blockade conditions." (PMID 32183814, 2020). "Previous study showed that the subepithelial layer was enriched with CD4+ T cells in colitis induced by CTLA-4 inhibitors." (PMID 33123120, 2020). "The incidence of diarrhoea and colitis related to CTLA-4 inhibitors is higher at 35% and 10%, respectively and more severe compared to that induced by PD-1 blockade with 20% and 1.6%, respectively." (PMID 33228219, 2020). "When we analyzed all older adults who received anti-CTLA-4 in any line of treatment, 134 of the 893 patients developed a 3–4 grade colitis (15.0%)." (PMID 32726988, 2020). "Increased representation of Bacteroides fragilis, Burkholderia cepacia and the Faecalibacterium genus in the GI tract of patients receiving CTLA-4-based immunotherapy led to a stronger therapeutic effect while minimizing adverse side effects such as colitis." (PMID 32944086, 2020). "We found that Tα1 protects mice from anti–CTLA-4–induced colitis by engaging the IDO1 tolerogenic pathway in the gut, while sustaining the antitumor activity via DCs and lymphocyte infiltration at the tumor site." (PMID 32817121, 2020). "Deaths from a combination of anti-CTLA-4 and anti-PD-1 were mainly from colitis at 33% and 25% by myocarditis." (PMID 32679922, 2020). "We used dextran sulfate sodium (DSS)-induced colitis mice as our model and tested the possibility of using a trafficking-blocking antibody to treat anti-CTLA-4 antibody-induced irAEs." (PMID 32183814, 2020). "There were 193 anti-CTLA-4-related deaths (mostly from colitis at 70%) and 333 deaths from anti-PD-1/PD-L1 treatments (mostly from pneumonitis at 33%)." (PMID 32679922, 2020).
colitis (continued). "prospectively analyzed the baseline microbiome composition of 34 anti-CTLA-4 treated patients of whom 10 developed colitis using 16S rRNA and metagenomic shotgun sequencing." (PMID 33643899, 2020). "As an example, colitis occurs more frequently in anti-CTLA-4 treated patients while thyroid disorders are more frequently seen during anti-PD-1 therapy." (PMID 33643899, 2020). "Colitis is one of the most common irAEs, and the incidence of colitis ranges between 5% for PD-1 and PD-L1 and 25% for CTLA-4." (PMID 32190487, 2020). "Blocking T cell homing increased colitis severity under CTLA-4-blockade conditions, which contrasted with our expectation." (PMID 32183814, 2020). "The Bacteroidetes phylum of the intestinal microbiota has been identified to be protective against anti-CTLA-4-induced colitis by stimulating the differentiation of regulatory T-cells, thereby limiting inflammation." (PMID 32726988, 2020). "Our funding provides a caution for applying a trafficking-blocking antibody to treat CTLA-4 blockade-induced colitis." (PMID 32183814, 2020). "A recent meta-analysis showed that most of CTLA-4 deaths occurred in patients who experienced colitis, while fatalities related to PD-1/PD-L1i occurred in patients who experienced pneumonitis, hepatitis, and neurotoxic effects." (PMID 32581796, 2020). "Depletion of CD4 T-cells and macrophages reduced combination anti-PD-1/CTLA4 (Fc-effector)-mediated colitis and inflammation of the small intestine." (PMID 33127658, 2020). "Patients experience immune-related adverse events such as colitis, hypothyroidism, hepatitis, hypophysitis, hyperthyroidism, and pneumonitis, which are significantly escalated when combined with anti-CTLA-4 and anti-PD-1 therapy." (PMID 33297519, 2020). "For example, in PD-1 inhibitor-induced colitis, CD8+ T cells exist in the lamina propria and epithelium, whereas the same T cells exist in the lamina propria in CTLA-4 inhibitor-induced colitis." (PMID 31182061, 2019). "One third of patients treated with ipilimumab, an anti-CTLA-4 antibody, develop diarrhea and 16% of patients will go on to develop severe colitis, which can lead to perforations (0.5%) and/or colectomy." (PMID 31383006, 2019). "Overt colonic inflammation after anti-CTLA-4 and/or anti-PD-1/PDL-1 immunotherapy is referred to as ICB associated colitis." (PMID 31214189, 2019). "The rate of IMDC in the current study was slightly higher than what was reported as the overall incidence of any grade diarrhea or colitis, likely because almost half of the current cohort received CTLA-4 inhibitors." (PMID 31488205, 2019). "Combination PD-1/CTLA-4 related deaths were recently found to be most frequently from colitis, accounting for 37% of fatalities." (PMID 31293970, 2019). "We interpreted the colitis most likely as a consequence of CTLA-4 blockade and therefore decided to continue the PD-1 blocking antibody nivolumab alone." (PMID 30791949, 2019). "Our results with the B16 tumor model and DSS colitis are consistent with the clinical observations in patients who received ipilimumab (anti-CTLA-4 antibody), and/or nivolumab (anti-PD-1 antibody)." (PMID 31214189, 2019). "The oral feeding of B. fragilis and B. cepacian to mice can restore the response to anti-CTLA4 and significantly decrease the extent of immune-mediated colitis." (PMID 31293523, 2019). "Intestinal reconstitution of antibiotic-treated mice with Bacteroides fragilis and Burkholderia cepacia was also shown to reduce anti-CTLA-4-induced colitis." (PMID 30887236, 2019). "The incidence of colitis ranges from 8 to 27% with rates of diarrhea reported up to 54% of CTLA-4 treated patients." (PMID 31293970, 2019). "A recent meta-analysis revealed that colitis, hypophysitis and rash were more frequent with anti-CTLA-4 antibodies whereas pneumonitis, hypothyroidism, arthralgia, and vitiligo were more common with anti-PD-1 antibodies." (PMID 31192215, 2019).
colitis (continued). "Patients receiving CTLA-4 therapy more commonly present with colitis and hypophysitis, while patients receiving PD-1 therapy more commonly present with pneumonitis and thyroiditis." (PMID 31293970, 2019). "The abundance of Bacteroidetes in new-onset, immune-mediated colitis patients who were administered anti-CTLA-4 therapy was significantly lower than in colitis-free individuals receiving ipilimumab." (PMID 31293523, 2019). "Colon biopsies revealed regenerative changes of crypt epithelia and focal surface epithelial defects suggestive of an immune-mediated colitis under PD-1 and CTLA-4 blockade." (PMID 30791949, 2019). "Patients treated with CTLA-4 therapy with a predominance of bacteria from the Bacteroidetes phylum were found to have reduced rates of ipilimumab-induced colitis." (PMID 31293970, 2019). "Diarrhea and colitis are more frequent and severe with anti-CTLA4 agents (all grades: 30%; grade 3–4: 10–16%) than with agents targeting the PD-1/PD-L1 axis (all grades: 11–16%; grade 3–4: 1–2%)." (PMID 30305177, 2018). "Grade 3/4 colitis accounts for 1–3% among patients treated with PD-1/PD-L1 inhibitors compared to 7–9% among patients treated with CTLA-4 inhibitors." (PMID 30170560, 2018). "Rikenellaceae are correlated with resistance to the development of colitis following CTLA-4 blockade and can limit inflammation by stimulating T-regulatory cell differentiation." (PMID 30405569, 2018). "According to previous reports, there is a difference in the frequency of diarrhoea/colitis after blockade between CTLA-4 and PD-1/PD-L1." (PMID 30170560, 2018). "More recently, administration of the antibiotic vancomycin to mice with colitis and treated with anti-CTLA-4 resulted in a more severe manifestation of the intestinal disease, while administration of Bifidobacterium alleviated the symptoms." (PMID 29789015, 2018). "Administration of Bacteriodales has subsequently been shown to reduce CTLA-4 blockade induced colitis in an antibiotic-treated mouse model." (PMID 30263059, 2018). "Although PD-1/PD-L1 inhibitors produce fewer side effects than CTLA-4 inhibitors, diarrhoea and colitis continue to be reported." (PMID 30170560, 2018). "The timing of colitis after anti-CTLA-4 therapy is variable, but generally occurs within weeks to a couple months after the initiation of therapy, though infrequently can occur even up to a year after the therapy has been discontinued." (PMID 30228268, 2018). "Doubtlessly, similar strategies are yet to be identified for colitis, as well as the many other organ-specific inflammatory diseases induced by CTLA-4 and PD-1/PD-L1 targeted therapies." (PMID 29230210, 2017). "Another recent study evaluating the influence of the intestinal microbiome on immunotherapy-related colitis found that increased Bacteroides representation within the gut correlated with resistance to anti-CTLA-4-induced colitis." (PMID 29088901, 2017). "Histologically, colitis that follows treatment with anti-CTLA-4 antibodies is characterized by neutrophilic inflammation with increased intraepithelial lymphocytes, crypt epithelial cell apoptosis and few or no features of chronicity." (PMID 29162153, 2017). "Much like knockout experiments in preclinical model organisms, by inhibiting CTLA-4 and observing colitis, we learn that CTLA-4 plays an important role in the regulation of gut homeostasis." (PMID 29230210, 2017). "Microbial richness, reflecting the number of unique phylotypes within a given sample, was found to be similar between patients who developed CTLA-4 blockade-induced colitis and those who remained C-F." (PMID 26837003, 2016). "Patients who had evidence of significant prior CTLA-4 related colitis should only be treated with HD IL-2 after endoscopic evaluation to ensure resolution of colitis." (PMID 27660706, 2016).